DPP4 (dipeptidyl peptidase 4)
Diseases named in the same sentence as DPP4 in open-access papers (continued):
Sharing a sentence is not in itself a finding about the gene and the disease.
cancer (continued). "Moreover, we offer evidence supporting that metformin combined with other clinical metabolic drug targets, such as mTOR and DPP4 inhibitors, could be repurposing as a strategy for treating cancer." (PMID 29899823, 2018). "In this study, we identified a set of associated DEGs (CD44, CTGF, DPP4, CRYAB, EGLN3, FGF1, and FOS) with at least one functional enrichment, such as “angiogenesis”, “binding of endothelial cells”, “development of blood vessel”, MAPK signaling, HCM, and pathways in cancer." (PMID 28623314, 2017). "The treatments analyzed (within 3 years prior to cancer diagnosis) were: insulin glargine, insulin detemir, human insulin, fast-acting insulin and analogues, metformin, sulfonylureas, repaglinide, thiazolidinediones, dipeptidyl peptidase-4 inhibitors, and alpha glucosidase inhibitors." (PMID 24278227, 2013). "Sulfonylureas and TZDs lack consistent anti-cancer activity, while SGLT2 and DPP-4 inhibitors exhibit preliminary promise." (PMID 39333445, 2024). "When CD26/DPP4 was known as ADCP, low levels of solubilized CD26 were found in total cancer-derived cell lines and homogenates of colon, kidney, lung and liver tumors." (PMID 39001488, 2024). "In their study, they observed a significant decrease in plasma DPP-4 levels in stage III cancer compared to stages I, II, and IV, considering the overall TNM staging of various cancers included in their analysis." (PMID 39390508, 2024). "In their studies, probes that target enzymes like g-glu, DPP4, CAPN1, LAP, PGP-1, and APN hold significant promise for detecting a variety of diseases, encompassing both cancer and infections." (PMID 38516394, 2024). "The mechanism of GLP-1 agonists is similar to that of DPP4 inhibitors, and the SGLT-2 inhibitor has been seen to suppress cancer development in vitro." (PMID 37185411, 2023). "In basic research, dipeptidyl peptidase IV (DPP4), a protein, was identified as a cancer-related item." (PMID 37185411, 2023). "On the basis of the numerous biological functions of DPP-4, some preclinical studies have shown a potential link between DPP-4 inhibitors and cancer progression-related processes, including cancer growth, metastasis, and chemotherapeutic resistance." (PMID 37760498, 2023). "CD26/dipeptidyl peptidase (DPP) 4 is a membrane-bound protein found in many cell types and has been suggested as a potential biomarker and target for cancer therapy." (PMID 36071454, 2022). "At least, dipeptidyl peptidase 4 (DPP4, EC 3.4.14.5) has been studied as a selective prodrug-activating enzyme in cancer cells." (PMID 36339537, 2022). "Before discussing the relationship between DPP-4i and cancer, it is necessary to introduce the pleiotropic effect of DPP-4 because the relationship between DPP-4i and cancer is the reverse of the relationship between DPP-4 and cancer." (PMID 35933633, 2022). "Consistently, studies on melanoma and colorectal cancer also showed that DPP-4 limited the migration of T cells and natural killer (NK) cells by mediating the cleavage of chemokines CXCL10 to promote cancer progression." (PMID 35933633, 2022). "In conclusion, our results indicate that the red fluorescent probe QA-2OMeSiR, which targets both DPP4 and PSA, is effective for the rapid detection of even borderline cancer lesions." (PMID 35650221, 2022). "Since the diverse biological functions of DPP-4, cancer-promoting cytokine/ chemokine modulation and ECM interaction would be relevant to cancer cell behavior, DPP-4 inhibitors also potentially influence cancer cell biology beyond blood glucose control." (PMID 34063285, 2021). "DPP-4/CD26 plays diverse pivotal roles beyond blood glucose control; thus, DPP-4 inhibitors can potentially impact cancer-bearing T2DM patients either favorably or unfavorably." (PMID 34063285, 2021). "However, also such a finding could be a sign of the risk of DPP-4 inhibitors in certain cancers, and it should not be overlooked." (PMID 34063285, 2021).
cancer (continued). "DPP4, ANPEP, and ENPEP RNA expression were also elevated in renal tumors compared to other cancer tissues." (PMID 33330620, 2020). "Here, the expression of five genes, known to encode coronavirus receptors/interactors (ACE2, TMPRSS2, CLEC4M, DPP4 and TMPRSS11D), was investigated in normal and cancer tissues, and their molecular relationships with clinical comorbidities were investigated." (PMID 32970391, 2020). "Dipeptidyl peptidase-4 (DPP4), an ubiquitously expressed transmembrane glycoprotein, is a possible marker for many cancers." (PMID 32294701, 2020). "Past studies suggest a protective role of DPP-4 inhibitors, but recent studies show that DPP-4 inhibition induces cancer metastasis." (PMID 32498358, 2020). "Assessment of known cell stemness biomarkers DPP4, CD44, MSI1 and ALCAM as well as autofluorescence showed that resistant cells are enriched with cancer stem cells." (PMID 31336714, 2019). "Recent evidence also suggests that the use of oral antihyperglycemic medications, like metformin, DPP‐4 inhibitors, and SGLT‐2 inhibitors, may improve overall and cancer‐specific survival, while sulfonylureas have often been associated with poorer survival." (PMID 41287203, 2026). "Our study found that SGLT-2 inhibitors may protect against cancer more than sulfonylureas, GLP-1 agonists, and DPP-4 inhibitors." (PMID 40290515, 2025). "Importantly, RNA-seq indicated DNAJC10 downregulates CAMs-related genes such as ITGAV, SEMA3C, DPP4, and ITGA1, which promote cancer cell migration and invasion." (PMID 41191192, 2025). "Unlike its well‐characterised family member DPP4, which has been extensively studied in cancer biology, the role of DPP7 in tumorigenesis remains largely unexplored." (PMID 40576169, 2025). "Furthermore, Heatmap analysis showed DNAJC10 overexpression reduced transcription of CAMs related genes such as ITGAV, SEMA3C, DPP4, and ITGA1, which are reported to enhance cancer cell migration and invasion." (PMID 41191192, 2025). "Novel antidiabetic medications (SGLT-2 inhibitors, DPP-4 inhibitors, and GLP-1 agonists) are commonly used worldwide; however, the available research lacks definitive conclusions on their protective effects or potential risks on cancer." (PMID 40290515, 2025). "To approximate saliva samples from cancer patients, where DPP-4 activity levels are 2–4 fold higher than in controls, we added DPP-4 to the saliva and found that we could easily detect these differences." (PMID 39439401, 2024). "Whereas other proteases involved in cancer development and progression are mainly degrading ECM proteins, the DPP4 enzymatic activity of CD26 shows a different character, modulating the biological activity of many regulatory peptides and, at least, participating in systemic homeostasis." (PMID 39001488, 2024). "Consistent with the spatial organization of these FAP+ CAF cluster-related ECT, we observe that cancer cells promote the differentiation of the Detox-iCAF cluster into Wound-myCAF and ECM-myCAF clusters through DPP4- and YAP1-dependent mechanisms both in vitro and in vivo." (PMID 38561380, 2024). "The DPP-4 inhibitor treatment significantly increased the cell proliferation detected by BrdU incorporation in MDA-MB-231 cancer cells, but not in MCF 10A normal cells." (PMID 37760498, 2023). "This review fundamentally focused on DPP-4 for the Special Issue “CD26 and cancer” in this journal." (PMID 34063285, 2021). "Based on the available clinical reports, however, the incidence of cancer is not significantly related to the DPP-4 inhibitor prescription when adjusted by cofounders." (PMID 34063285, 2021). "Their recruitment in response to the cancer-cell secreted alarmin IL-33, is mediated by the chemokine CCL11, and enhanced with the administration of sitagliptin, an inhibitor of dipeptidyl peptidase DPP4 (CD26) that cleaves CCL11." (PMID 33815418, 2021).
cancer (continued). "In the study, researchers suggested the correlation between DPP4-inhibitor administration and reduced risks of cancer and cancer mortality, whereas the overall mortality, regardless of the cause, remains consistent." (PMID 34298800, 2021). "How the use of DPP-4 inhibitors impacts the DPP-4 expression of cancer in diabetic patients is not yet elucidated." (PMID 34063285, 2021). "Based on the current evidence from large clinical trials, DPP-4 inhibitors are safe for human health without significant concern about new onsets of cancers." (PMID 34063285, 2021). "DPP-4 cleaves many substances, not only incretin hormones; DPP-4 inhibitors potentially increase many growth factors and chemokines that may induce cancer progression." (PMID 34063285, 2021). "In this context, DPP-4 could cleave/inactivate CXCL12 and downregulate the CXCL12/CXCR4 axis, subsequently inhibiting cancer cell growth, invasiveness and metastasis." (PMID 31991851, 2020). "Specifically, ACE2, TMPRSS2, CLEC4M, DPP4 and transmembrane protease serine 11D (TMPRSS11D) were analyzed by assessing their RNA expression levels in different body districts and in different cancer types." (PMID 32970391, 2020). "This study aims to compare the change of kidney function and the incidence of AKI in diabetic-cancer patients treated with cisplatin combined with or without DPP-4 inhibitors." (PMID 32084231, 2020). "Cancer cells also control the production and the activity of chemokines through the transcriptional silencing or the post-translational modifications, via dipeptidyl peptidase 4 (DPP4 or CD26)." (PMID 31216755, 2019). "For example, staining for CD26 (DPP4) in normal (A) and cancer (B) prostate tissue shows clear luminal staining, which corresponds with intense gene expression measured by array in the luminal and cancer (05-179_CD26t) cell populations." (PMID 18501003, 2008). "DPP-4 inhibition may elevate CXCL12 levels, potentially promoting metastasis in these cancers." (PMID 40282969, 2025). "Indeed, DPP4/CD26 could be a promising marker and a novel target to potentially decrease senescence escape in cancer." (PMID 38786063, 2024). "However, the influence of DPP-4 inhibition-induced autophagy on cancer cell progression-related processes has not been elucidated." (PMID 37760498, 2023). "Since DPP4 activity was not measured in this case, we are not able to know if its measurement would have contributed to the detection of cancer, in particular, because with both measures, the ratios of sCD26/DPP4 showed a wide range (from 4 to 22) and many were outliers." (PMID 36230486, 2022). "However, supplementation with recombinant DPP4 protein failed to promote cancer cell proliferation in vitro, suggesting that DPP4 did not directly affect cancer cell biology in vitro." (PMID 35053615, 2022). "Furthermore, a clinical report exploring the impact of DPP-4 inhibitors on chemotherapy outcomes in diabetic patients with cancer is lacking." (PMID 34063285, 2021). "Therefore, a prospective randomized trial to test the safety of DPP-4 inhibitors on cancer-bearing diabetic patients will never be performed." (PMID 34063285, 2021). "However, importantly, the safety profile of a DPP-4 inhibitor (the same as other anti-diabetic drugs) on cancer progression of existing cancer or recurrence has not yet been established." (PMID 34063285, 2021). "As the expression of DPP4 increased in the adipose tissue of obese patients and some specific cancer patients, it was anticipated to reduce the infection rate of SARS-CoV-2 in patients by treatment with DPP4 inhibitors, while further clinical trials are needed to verify our hypothesis." (PMID 33614513, 2021). "Therefore, the pleiotropic effects of DPP-4 inhibitors would not always be favorable, especially in cancer-bearing T2DM patients." (PMID 34063285, 2021). "However, the mechanistic consequences of DPP-4 inhibition for a cancer-bearing individual are still not completely understood." (PMID 34063285, 2021).
cancer (continued). "Consistent with this notion, we identified a subset of this signature containing DPP4, BCAT1, CNTNAP4 and CDH3, whose expression are either the same or increased in CRPC compared to primary PC, and whose gene alterations correlate with a more rapid onset of cancer." (PMID 28055971, 2017). "Even though the physiological role of serum/plasma soluble CD26 (sCD26) protein with dipeptidyl peptidase 4 (DPP4, EC 3.4.14.5) activity as a ligand remains unclear (several possibilities have been reported in recent years), increasing evidence suggest that it can work as a biomarker in cancer." (PMID 39001488, 2024). "In view of the profiles of DPP4 expression and the correlation with immune cells and various pro-inflammatory cytokines and chemokines in LUSC patients, DPP4 might have a great potency in exacerbating the cytokine storm in specific cancer patients after SARS-CoV-2 infection." (PMID 33614513, 2021). "Sulfonylureas and TZDs have not demonstrated consistent anti-cancer activity, while SGLT2 inhibitors and DPP-4 inhibitors have shown some potential benefits." (PMID 39333445, 2024).
infection (174 papers, 2005 to 2026). The state of being infected such as from the introduction of a foreign agent such as serum, vaccine, antigenic substance or organism. "Here, we provide evidence that viruses recently circulating in Arabian camels and causing human infections are less susceptible to inhibition by human soluble DPP4 (sDPP4)-a secreted version of the viral receptor that is present in various bodily fluids." (PMID 41940670, 2026). "Inhibition of these receptors by the DPP-4 inhibitor, sitagliptin, can reduce the pathogenesis of the infection caused by SARS-CoV-2 and their associated activation of the inflammatory signaling pathways." (PMID 36180664, 2022). "Human anti-CD26/DPP4 antibodies inhibited infection of susceptible bat (RoNi/7.1) cells and Huh-7 cells, in a dose-dependent manner." (PMID 34239932, 2021). "There have been concerns raised about increased risk of infections associated with use of DPP4 inhibitors due to its immune modulating effects." (PMID 33261058, 2020). "For all-cause mortality and infection related death, the pioglitazone group had a consistent lower HR when compared with the DPP4-inhibitors group in specific subgroups." (PMID 33172034, 2020). "Infection with MERS-CoV is initiated by the binding of MERS-CoV spike protein to DPP4; a process that causes virus-cell fusion." (PMID 33324223, 2020). "A nested control study based on the World Health Organization Vigibase9 showed that DPP-4 inhibitor use was associated with a greater risk of infection compared with metformin use." (PMID 26463557, 2015). "Human anti-CD26/DPP4 antibodies inhibited infection of susceptible bat cells in a dose-dependent manner." (PMID 25409519, 2014). "In addition to its multiple physiological roles, DPP4 was implicated in many pathological conditions including infection." (PMID 35413090, 2022). "In addition, the concentration of infection in the lower respiratory tract caused by the location of DPP4 leads to more severe disease." (PMID 35576224, 2022). "Moreover, this infection caused the dramatic depletion of the surface receptor dipeptidyl peptidase 4 (DPP4) impacting T cells proliferation and functionality and so inducing apoptosis." (PMID 34201847, 2021). "Based on this observation, we speculate that in some individuals, DPP4 expression may actually be low enough-due to genetics or other factors-to reduce susceptibility to infection and/or replication by MERS-CoV." (PMID 35059374, 2021). "Another conceivable cause of reduced DPP4+ T cell frequencies might lie in the early infection and destruction of memory/helper T cells expressing the CD4+CD45RO+CD26+ phenotype." (PMID 32946499, 2020). "In order to analyze whether the reduction in MERS-CoV S-driven host cell entry would translate into attenuated MERS-CoV replication, we next investigated two DPP4 polymorphisms (K267E and A291P) in the context of infection with authentic MERS-CoV." (PMID 31964246, 2020). "There was also some concern over increased susceptibility to infection with DPP4 inhibitors." (PMID 29535389, 2018). "The balance between immune inhibition and anti-inflammation may be responsible for infection risk in DPP-4 inhibitor users." (PMID 26463557, 2015). "Our study is limited in that sDPP IV concentration and DPP4 genotyping was performed only for limited number of patients with HCV genotype 1 infection, since previous data had found that the association with SVR was found in HCV genotype 1, and this was a secondary objective." (PMID 26339796, 2015). "As for the infection of MERS-CoV, a recent study demonstrated that the infection of human DPP4-transduced and T cell-deficient mice with MERS-CoV resulted in the persistence of MERS-CoV in the lungs while the virus was cleared in control mice and B cell-deficient mice." (PMID 26690369, 2015).